HSF1 (heat shock transcription factor 1)
Diseases named in the same sentence as HSF1 in open-access papers (continued):
Sharing a sentence is not in itself a finding about the gene and the disease.
breast cancer (continued). "In many solid tumors, HSF1 and HSF2 interact and together modulate subsets of genes fundamental for disease progression, whereas in breast cancer HSF2 alone has been shown to promote the abnormal proliferation of cancer cells." (PMID 40245053, 2025). "During acute stress the interplay between HSFs sustains an optimal cellular response, whereas in other physiological and pathological processes such as erythroid differentiation and breast cancer progression, HSF2 operates independently from HSF1." (PMID 40245053, 2025). "A substantial positive correlation was observed between HSF1 and either ALDH1A1 (p = 0.0009) or CD44 (p < 0.0001) in breast cancer patients with high HER2 expression." (PMID 38646654, 2024). "In another study, the overexpression of Bag-1, another protein from the BAG family, modulates HSP levels by phosphorylating HSF1 at Ser326 via the PI3K/AKT/mTOR pathway in HER2-positive and HER2-negative breast cancer cells." (PMID 39850800, 2024). "The phosphorylation of HSF1 (threonine 120) by PIM2, an oncogenic serine/threonine kinase, plays a crucial role in up-regulating the expression of PD-L1 in breast cancer cells." (PMID 37153737, 2023). "HSF1 is also involved in the activation of HER2, an EGFR family member, which plays a critical role in breast cancer." (PMID 37153737, 2023). "Some data indicate that the heat shock factor 1 (HSF1), a well-known regulator of stress response, can promote TGFβ-induced EMT in the ovarian cancer model or in the breast cancer model." (PMID 37894333, 2023). "Therefore, HSF1 inhibition could be tested as an adjuvant treatment for breast cancer patients." (PMID 37894333, 2023). "Interestingly, HSF1 could induce PD-L1 expression and enhance tumor growth in breast cancer." (PMID 35006040, 2022). "This is in agreement with the recent report on the cooperation of HSF1 with the estrogen receptor, and on the other hand, indicates that MCF7 cells are a good model cell line for ER-positive breast cancer." (PMID 36010586, 2022). "Other typical HSF1 targets upregulated by heat shock (e.g., HSPA1A, HSPA1B, HSP90AB1) showed higher expression levels in all HSF1high breast cancers." (PMID 36010586, 2022). "This analysis was performed using TCGA datasets for breast cancer (BRCA) and colorectal adenocarcinoma (COADREAD) wherein patients for each dataset were scored for HSF1 activity using the HSF1 CaSig." (PMID 35080342, 2022). "We additionally compared the expression of E2-regulated genes (the set identified in MCF7 cells by RNA-seq, i.e., 46 upregulated and 2 downregulated genes) in selected groups of breast cancers with different levels of ESR1 and HSF1." (PMID 34783649, 2021). "Furthermore, the prognostic value of both ESR1 and HSF1 was visible in such homogenous groups, which may simply reflect the prognostic difference between the basal-like and luminal A (i.e., ER-negative and ER-positive) breast cancer subtypes." (PMID 34783649, 2021). "In agreement with our observations, forced overexpression of HSF-1 increased mammosphere-forming ability as well as CD44, Sox2 and ALDH1 expression, and conferred drug resistance in breast cancer, while HSF-1 knockdown attenuated these phenomena." (PMID 34775489, 2021). "The expression of Hsp70 and Hsp27 is induced by the transcription factor HSF1, which also regulates glucose metabolism and has been shown to increase the LDHA expression in breast cancer cells by binding to the LDHA promoter." (PMID 34359663, 2021). "Subsequently, HSF1-null mice were also shown to be resistant to carcinogen-induced liver cancer and HER2/ErbB2-induced breast cancer." (PMID 32408596, 2020). "The transcription factor IER5, which is upregulated in the breast cancer cell lines MCF-7 and MDA-MB-231, was found to induce abnormal HSF1 activation, which subsequently promoted anchorage-independent cell growth." (PMID 32408596, 2020).
breast cancer (continued). "In MCF-7 breast cancer cells, the serine/threonine-protein kinase PIM2 phosphorylates HSF1 at threonine 120, which disrupts the interaction between FBXW7 and HSF1 and increases HSF1 protein stability." (PMID 32408596, 2020). "Inhibition of HSF1 blocked TGFβ‐, FAM3C‐ and YY1‐induced proliferation and migration of breast cancer cells." (PMID 30887707, 2019). "In human MDA‐MB‐231 breast cancer cell line, transforming growth factor‐β (TGFβ) up‐regulated FAM3C, HSF1 and YY1 expressions." (PMID 30887707, 2019). "This study determined the role and mechanism of YY1 and HSF1 in FAM3C‐induced proliferation and migration of breast cancer cells." (PMID 30887707, 2019). "However, whether co-activation of AKT and HSF1 occurs in other breast cancer subtypes is unknown." (PMID 29088759, 2017). "Our lab has recently reported that AKT activates heat shock factor 1 (HSF1), leading to epithelial-to-mesenchymal transition in HER2-positive breast cancer." (PMID 29088759, 2017). "HSF1 has also been shown to be involved in hepatocellular carcinoma development, as well as induction of a CSC-like phenotype in breast cancer cells." (PMID 28241425, 2017). "The combination of small molecule inhibitors targeting AKT (MK-2206) and HSF1 (KRIBB11) resulted in synergistic killing of breast cancer cells and breast cancer stem cells across different molecular subtypes." (PMID 29088759, 2017). "pS326 has been shown to positively regulate HSF1 transactivation on HSE-containing promoters in HeLa cervical carcinoma cells and MDA-MB-231 breast cancer cells." (PMID 27487129, 2016). "Previous work of our group revealed that HSF1 inhibition by NZ28 increases the radiosensitizing efficiency of the Hsp90 inhibitor NVP-AUY922 in lung and breast cancer cell lines (unpublished data)." (PMID 25854583, 2015). "For example, in breast cancer, FUT4 transcription is regulated by HSF1 and Sp1 to inhibit cell proliferation; in HaCaT cells, FUT4 level is lower due to the higher methylation of CpG island in FUT4 promoter." (PMID 26094873, 2015). "NZ28 down-regulated the HSF1 activity and the MICA/B expression on lung and mammary tumor cells, and this correlated with a reduced sensitivity to NK cell-mediated lysis." (PMID 25854583, 2015). "Expression of LDH depends on HSF1, which binds to the LDHA gene promoter in human breast cancer cells overexpressing ERBB2." (PMID 24467529, 2014). "The impact of HSF1 on glucose metabolism was also confirmed by the finding that HSF1 directly activates the LDHA gene, which supports “addiction to sugar” in human breast cancer cells." (PMID 24467529, 2014). "Further studies are needed to examine the contribution of HSF1 and BRCA1 depletion to the anticancer effects of WA in breast cancer." (PMID 25969759, 2012). "Further studies are warranted to examine the contribution of HSF1 and BRCA1 depletion to the anticancer effects of WA in breast cancer." (PMID 25969759, 2012). "It is intriguing that MG132 alone induced a decrease in both HSF1 and BRCA1 protein levels in Triton-soluble fractions while inducing an increase in their levels in Triton-insoluble fractions of breast cancer cell protein extract." (PMID 25969759, 2012). "HSF1, the transcription factor for heat shock proteins (HSP), has recently been shown as a facilitator of transformation in breast cancer." (PMID 21978374, 2011). "For instance, in breast cancer a highly predictive consensus decision module was identified among C/EBPβ, STAT5A, and HSF1 – three genes whose activity has been shown to directly influence cancer progression." (PMID 21980275, 2011).
breast cancer (continued). "In many human cancers including HCC, breast cancer, endometrial carcinoma, oral squamous cell carcinoma or prostate cancer; increased HSF1 levels compared to non-cancerous tissues are observed." (PMID 40287736, 2025). "In HCC, breast cancer, prostate cancer, lung cancer, esophageal squamous cell carcinoma (ESCC), and colorectal cancer (CRC), HSF2 and HSF4 are frequently dysregulated, while HSF1 is highly expressed across all these cancers." (PMID 39248163, 2024). "In addition, this study showed that HSF1 regulated ERα expression levels in ER+ MCF-7 and T-47D breast cancer cells." (PMID 38567308, 2024). "In a previous study, it has been demonstrated that HER2 overexpression triggers activation of the HSF1-HSP90 axis and subsequently leads to the stabilization of HSP90 client proteins such as AKT, mTOR and HSF1 itself, thereby promoting tumor growth in HER2-positive breast cancer." (PMID 38646654, 2024). "HSF1 was also suggested to regulate the expression of PD-L1 in breast cancer, but consistent observations have not been found in other cancers, including PDAC." (PMID 39350280, 2024). "Surprisingly, in our model, the increase in HSF1 expression did not affect the stem cell-like characteristics of MD-MB-468 breast cancer cells (which exhibit CD44pos/CD24pos) but facilitated their migration and growth in Matrigel." (PMID 37894333, 2023). "Taking into account our observation that HSF1 may play a role in the EMT of human mammary epithelial cells, we examined the correlation between HSF1 levels and the phenotype of breast cancer cells." (PMID 37894333, 2023). "To test whether HSF1 can change the phenotype of breast cancer cells from epithelial-like toward mesenchymal, we constructed MDA-MB-468 cells with HSF1 overexpression." (PMID 37894333, 2023). "Because of the substantial co-overexpression of GSDMD and HSF1 in breast cancer, this serendipity observation allowed us to postulate that the genes residing in between the GSDMD and HSF1 loci might also be upregulated in breast cancer." (PMID 36497066, 2022). "A similar response of HSF1 to MA that was accompanied by overproduction of HSPA1 and HSPA6 expression and HSPA2 downregulation was also observed in the wild type (wt) MCF7 breast cancer cell line." (PMID 34200371, 2021). "Indeed, in breast cancer cells, TGF-β induces the activation of HSF1-Akt-CyclinD1 pathway through the FAM3C protein, promoting tumor proliferation and migration." (PMID 34198675, 2021). "(A) Correlation of HSF1 and ESR1 transcript level in all TCGA breast cancers." (PMID 34783649, 2021). "Indeed, it was demonstrated that HSF1 promotes TGFβ-induced EMT, tumorigenesis, and metastases in a murine breast cancer model; the EMT-promoting mechanism was due to HSF1-mediated stimulation of the RAS/RAF/MEK/ERK1/2 signaling pathway." (PMID 32268506, 2020). "Interestingly, HSF1 and HSF2 displayed the second highest correlation, providing evidence in support of a cooperative interaction in breast cancer." (PMID 33184288, 2020). "In human breast cancer tissues, FAM3C, YY1 and HSF1 protein expressions were increased." (PMID 30887707, 2019). "Similarly, inhibition of HSF1 also blunted FAM3C‐ and TGFβ‐promoted proliferation and migration of human breast cancer BT‐549 cells." (PMID 30887707, 2019). "Therefore they suggested and subsequently also reported that trastuzumab inhibits glycolysis through downregulation of the HSF1-LDHA axis and, moreover, this axis contributes to the resistance of breast cancer cells to this monoclonal antibody." (PMID 29455660, 2018). "Furthermore, the HSF1-mediated DDR mechanisms protect tumor cells from DNA damage, especially supporting growth of BRCA1-null mammary tumors, which are sensitive to PARP inhibitors." (PMID 29158484, 2017).
breast cancer (continued). "High expression of HSF1 was significantly associated with shorter overall survival (ANOVA; P = 0.00045), and relapse-free survival (ANOVA; P = 0.0057) in ER-positive breast cancer patients, but not in ER-negative tumors (data not shown)." (PMID 27713164, 2016). "Reduction of Hsf1 reduces HSPB7 and inhibits EMT and tumorigenesis in mouse breast cancer models." (PMID 27876705, 2016). "Since the current literature suggested an association of HER2+ breast cancer with HSF1 but not with LSP1, we further analyzed the differential affinity of variant and ancestral miR-608 to the 3′UTR of HSF1." (PMID 22586447, 2012). "AKT phosphorylates HSF1 independent of heat stress in breast cancer cells." (PMID 39433125, 2024). "Since the initial observation that S326 phosphorylation affects heat stress‐induced HSF1 activity, five kinases have been observed to phosphorylate S326, including mTORC1, MEK1, p38, DYRK2 and AKT1, which our work previously identified can phosphorylate S326 in breast cancer." (PMID 35080342, 2022). "The mechanism of supportive action of HSF1 in ER-positive cells was already proposed, by which upon E2 treatment HSF1 is phosphorylated via ERα/MAPK signaling, gains transcriptional competence, and activates several genes essential for breast cancer cell growth and/or ERα action." (PMID 34783649, 2021). "Importantly, the NRF2–HSF1 axis was found to play an important role in MCF-7 malignancy, since interfering with NRF2-mediated HSF1 activation also suppressed the survival, migration and the expression of E-cadherin and N-cadherin, two markers of EMT in MCF7 breast cancer cells." (PMID 33805996, 2021). "Our results showed that HSF1 protein is expressed in the epithelial cells of the non-cancerous tissues, though at a low level, however, its expression is significantly increased in all breast cancer patients investigated in this study, as seen by IHC results." (PMID 29494616, 2018). "Moreover, Scherz-Shouval's study observed increased HSF1 expression in stromal cells but not in tumor cells, which is an indispensable prognostic marker for breast cancer and lung cancer." (PMID 26511079, 2015). "Spontaneous rat mammary tumors that overexpressed HSF1 that developed in response to DMBA showed aggressive carcinogenesis with inhibition of binding activity between Ku70 and Ku80, suggesting a physiological role for HSF1 in tumor development by inhibition of NHEJ repair activity." (PMID 26359349, 2015). "Thus, in the present study, we investigated the hypothesis that downregulation of the heat shock response by gene-editing knockdown of HSF1, or by a specific chemical inhibitor of HSF1: KRIBB11, enhances the therapeutic efficiency of mEHT in breast cancer treatment." (PMID 38589452, 2024). "However, independent of the heat shock response, HSF-1 has been reported to support malignant features such as cell cycle regulation, signaling, metabolism, adhesion, and translation in various cancers including breast cancer." (PMID 38081808, 2023). "In addition, analyses of the transcriptome of breast cancers from TCGA database showed the importance of HSF1 as evidenced by higher transcriptome disparity in ER-positive cases with a high expression of HSF1 rather than with low HSF1 levels." (PMID 34783649, 2021). "HSF1 is overexpressed in several cancer types, including colorectal cancer (CRC), esophageal squamous cell carcinoma (ESCC), breast cancer (BC), hepatocellular carcinoma (HCC), osteosarcoma, non-small-cell lung cancer, clear cell renal cell carcinoma (ccRCC), etc.." (PMID 30326922, 2018). "The absence of HSF1 prevents the ATG7 promoter activity and increases the chemosensitivity to carboplatin in the MDA-MB-231 breast cancer cell line." (PMID 39850800, 2024). "Treatment with HVH-2930 was observed to alleviate HSF1 phosphorylation, thereby preventing nuclear accumulation and HSP70 upregulation in HER2-positive breast cancer cells, without inducing HSF1 transcriptional activity." (PMID 38646654, 2024).
breast cancer (continued). "Treatment with NCT-58 did not induce the HSR, as evidenced by the absence of nuclear accumulation of HSF-1 and upregulation of HSP70 expression in HER2-positive breast cancer cells." (PMID 34775489, 2021). "Furthermore, amplification of HSF1 was correlated with higher HSP90AA1 and HSP90AB1 mRNA expression among the breast cancer cells without amplifications of these two genes." (PMID 22510516, 2012). "A prior report has suggested that AKT may have a direct effect on HSF1 activity: under normal growth conditions, in the absence of heat shock, AKT increased HSF1 activity, which, in turn, increased the expression of certain markers of epithelial–mesenchymal transition (EMT) in breast carcinomas." (PMID 34768807, 2021).